NLRP3 (NLR family pyrin domain containing 3)
Diseases named in the same sentence as NLRP3 in open-access papers (continued):
Sharing a sentence is not in itself a finding about the gene and the disease.
Stroke (continued). "This may be due to the fact that the nature of acute inflammation in ACS is amplified by HSUA-induced oxidative stress and NLRP3 inflammasome activity, and these effects could cause inconsistent early outcomes like faster myocardial ischemia or stroke." (PMID 41584288, 2025). "Briefly, genetic mutations encoding the NLRP3 inflammasome are linked to stroke prognosis." (PMID 41542272, 2024). "After a stroke, mitochondria govern the NLRP3 inflammasome by discharging molecular contents, which release pro-inflammatory cytokines such as IL-1β and IL-18, driving the inflammatory response, potentially linked to post-stroke depressive-like behaviors." (PMID 38377025, 2024). "Our study demonstrated that after NLRP3 KO, NLRP3-related proteins were downregulated, since lung NLRP3 was reduced and lung damage resulting from the relief of brain damage was alleviated, demonstrating that neuroinflammation caused by stroke can adversely affect the lungs." (PMID 35432726, 2022). "Once confirmed, a higher level of NLRP3 at an early stage of stroke may help to identify patients at a high risk for MBE." (PMID 34493232, 2021). "NLRP3 inflammatory response is associated with microglia activation which maybe contributed to the neuron recovery after stroke though NF-κB and caspase 1 activation." (PMID 32908485, 2020). "NLRP3 inflammasome activation plays a critical pathogenic role in strokes." (PMID 32419986, 2020). "Sensing several stroke-induced stimuli, the cytosolic pattern recognition receptor NLRP3 recruits the adapter protein the apoptosis-associated speck-like (ASC) pro-caspase-1 leading to caspase-1 production and subsequent interlukin-1 β (IL-1β) maturation and release." (PMID 29654318, 2018). "Moreover, recent studies have demonstrated that thioredoxin-interactive protein (TXNIP) activation is a key event linked to inflammation; after stroke, it dissociates from the complex and rapidly binds to NLRP3 inflammasome via reactive oxygen species (ROS)." (PMID 27589720, 2016). "Additionally, iTBS may protect against motor deficits and neuronal damage caused by stroke by inhibiting the TLR4/NF-κB/NLRP3 signaling pathway, thereby regulating the M1/M2 phenotype balance in microglia." (PMID 39719979, 2024). "In this review we summarize the current understanding of the underlying role of the NLRP3 inflammasome as well as highlight the current strides made in targeting the inflammasome as a modality to attenuate the effects of ischemic injury on brain tissue after a stroke event." (PMID 41542272, 2024). "Furthermore, NLRP3 deficiency was found to be beneficial as it could improve the neurovascular damage after stroke in mice." (PMID 32635451, 2020). "To further verify the mechanism by which 3‐HKA inhibits the activation of the AIM2 inflammasome after stroke, we also examined the mRNA expression of other Nod‐like receptors, such as NLRP3, NLRP1a and NLRC4." (PMID 39854137, 2025). "Association between serum NLRP3 inflammasome and occludin levels with gender, infarction volume, TOAST subtypes and stroke severity." (PMID 41408503, 2025). "This study examined brain tissue samples from stroke patients and revealed increased levels of IL-1β, IL-18, and the NLRP3 inflammasome protein." (PMID 40075143, 2025). "The current study’s findings demonstrated that hypoxia–ischemia insult activated the NLRP3 inflammasome in the photothrombotic stroke model in mice, resulting in brain damage." (PMID 40272769, 2025). "This aligns with research showing that inhibiting the thalamic NLRP3 inflammasome reduces IL‐18 and IL‐1β, leading to behavioral alleviation of thermal and mechanical pain sensitivity in a central post-stroke pain mouse model." (PMID 40329125, 2025). "Although NLRP3 deficiency decreased brain injury in and in an animal model of stroke, mounting evidence suggests that the levels of NLRP3-inflammasome and IL- 1 were elevated in the brain injury." (PMID 40272769, 2025).
Stroke (continued). "According to recent studies, the suppression of NLRP3 inflammasome modulates ischemic insult and neurovascular consequences of experimental stroke." (PMID 40272769, 2025). "In ischemic stroke, various studies on mouse and rat models have demonstrated the presence of pyroptosis-specific markers in the brain tissue after stroke, such as NLRP3, caspase-1/11, and GSDMD." (PMID 40343197, 2025). "Conversely, the lowest levels of NLRP3 inflammasome and occludin were more commonly found in patients with small artery occlusion and other types of stroke." (PMID 41408503, 2025). "After a stroke, RNA sequencing showed an increase in genes associated with the TREM-1 and NLRP3 pathways, including Nfkb2 and IL-1β, which contribute to the neuroinflammatory response immediately after ischemia." (PMID 40867169, 2025). "Among these mediators, the NOD-like receptor family pyrin domain-containing 3 (NLRP3) has gained particular attention as a critical driver of stroke-related neurovascular injury." (PMID 41408503, 2025). "The AUC value for serum NLRP3 inflammasome predicting poor stroke outcomes was 0.663 (95%CI 0.577–0.749, p = 0.001), with an optimal cut-point value of 82.75 pg/mL (sensitivity 43.1% and specificity 82.7%)." (PMID 41408503, 2025). "GSDMD, the pyroptosis executioner, was also predominantly expressed in microglia/macrophages, indicating that NLRP3 inflammasome‐mediated pyroptosis was mainly localized to microglia/macrophages after stroke." (PMID 39467260, 2025). "The degree of NLRP3 activation after stroke is closely related to the volume of cerebral infarction and inflammatory cell infiltration." (PMID 41451361, 2025). "Treatment with MCC950 after stroke can reduce the expression of various proinflammatory cytokines and components of the NLRP3 inflammasome, thereby decreasing infarct volume in a dose-dependent manner." (PMID 40075143, 2025). "Future research should directly compare untreated WT and NLRP3 KO mice to completely clarify the role of the NLRP3 deficit in stroke prevention." (PMID 40272769, 2025). "Another typical NLRP3 inflammasome inhibitor, CY-09, was also found to improve brain inflammatory cell death after stroke." (PMID 40075143, 2025). "The extensive involvement of the NLRP3 inflammasome in brain damage following stroke makes it a significant target for treatment." (PMID 40075143, 2025). "Recent studies have demonstrated that inhibiting the NLRP3 inflammasome and enhancing autophagy levels can markedly mitigate stroke-induced damage." (PMID 39690856, 2025). "In rodent stroke models, 10 days of treadmill training reduced NLRP3 expression by 50% and suppressed inflammasome-mediated pyroptosis by shifting microglial polarization toward the neuroprotective M2 phenotype." (PMID 40256392, 2025). "Remarkably, in clinical studies, NLRP3 inflammasome components and IL-1β and IL-18 were found to be upregulated in postmortem brain tissue samples from patients with stroke." (PMID 40343197, 2025). "Laboratory studies have demonstrated VNS improves neurologic function after stroke, in part by vagal-mediated suppression of the NLRP3 inflammasome exacerbating ischemia/reperfusion injury through neuroinflammation." (PMID 41455014, 2025). "Numerous studies have demonstrated the involvement of NLRP3 inflammasomes in both neuronal cells and microglia, with significant implications for stroke pathology." (PMID 39690856, 2025). "Neutrophil infiltration is a key marker of metabolic dysregulation in stroke, and we previously showed that suppression of NLRP3 can attenuate hemorrhagic transformation in thromboembolic stroke rats via reducing the neutrophil recruitment." (PMID 39021802, 2024). "Our results highlighted the clinical relevance of microinfarct on subsequent stroke and pointed out the importance of NLRP3 as a potential therapeutic target to mitigate recurrent stroke in CMI patients." (PMID 38216560, 2024).
Stroke (continued). "The data from this study further revealed that NLRP3 had an inflammasome-independent role in exacerbating subsequent stroke." (PMID 38216560, 2024). "Inhibit the activation of NLRP3 inflammasome and Caspase-1, and to regulate their upstream related signaling pathways, reduce post-stroke pyroptosis and the related inflammation." (PMID 39312329, 2024). "The interaction between nuclear NLRP3 and MLL1 is critical in CMI-induced trained immunity as the knockout of microglial NLRP3 inhibits trained immunity and attenuates recurrent stroke." (PMID 38216560, 2024). "The study results also highlighted the influence of trained immunity on recurrent stroke and provided a novel insight on the influence of NLRP3 in this innate immunity memory formation." (PMID 38216560, 2024). "Inhibition of the NOD-like receptor protein 3 (NLRP3) inflammasome was shown to diminish depression-like behavior in rats following stroke." (PMID 39618840, 2024). "High NLRP3 level has been observed in the ischemic brain of stroke animals, and NLRP3 inhibitor has been reported to alleviate ischemic brain damage in various stroke models." (PMID 38216560, 2024). "Exercise preconditioning inhibited the protein expression of NLRP3, Caspase-1, IL-18, and IL-1β to improve cognitive dysfunction in stroke mice." (PMID 38317957, 2024). "It is neuroprotective in animal models of stroke, inhibiting the activation of nucleotide-binding oligomerization domain-like receptor family pyrin domain-containing 3 (NLRP3) inflammasomes in a middle cerebral artery occlusion (MCAO) stroke model in mice." (PMID 38792655, 2024). "TAK1 (TGF-β activated kinase 1) has also been reported to induce NLRP3 assembly during stroke by activating NF-κB, increasing ROS release, and promoting lysosomal autophagy." (PMID 37165005, 2023). "The role of NLRP3 inflammasome in stroke was determined via various in vitro and in vivo research, which the viroporins of SARS-CoV2 can activate." (PMID 36969251, 2023). "STAMBP is a negative regulator of the NALP7 and NLRP3 inflammasomes, the latter of which has been identified as a potential therapeutic target to reduce pro-inflammatory stress after stroke." (PMID 37794467, 2023). "The most frequent keyword was NLRP3 inflammasome, followed by activation, stroke, oxidative stress, and nf–κb." (PMID 37088947, 2023). "Microglia‐mediated inflammasome activation also contributes to the stroke‐induced inflammatory response, wherein the inhibition of inflammasomes like NLRP3 plays an important role in neuroprotection." (PMID 37551863, 2023). "We found that the NLRP3 inflammasome was activated and cell pyroptosis was induced at 6 h and 24 h post-stroke in an ischemic brain." (PMID 37371374, 2023). "Idebenone, a mitochondrial protectant, has suppressed NLRP3 inflammation by mitigating mitochondrial dysfunction induced by cerebral ischemia/stroke and microglia overactivation to alleviate infarct volume and neurological deficit." (PMID 37915409, 2023). "Activation of AMPK by quercetin leads to the suppression of NF-kB and NLRP3 inflammasome activation, which in turn reduces inflammation in stroke." (PMID 37047299, 2023). "Further investigation is needed to determine the specific functions of NLRP3 in these different cell types and its implications for stroke pathology." (PMID 37822799, 2023). "NLRP3 inflammasome inhibition leads to a better long-term outcome—even when administered with a delay of 1 day after stroke induction, indicating ongoing inflammation-driven infarct progression." (PMID 36600259, 2023). "In fact, inactivation of endothelial adenosine A2A receptors attenuated ischemic brain injury and improved prognosis after stroke by inhibiting NLRP3 inflammasome activity." (PMID 37088947, 2023). "Our results demonstrate that the NLRP3 inflammasome continues to drive neuroinflammation within the subacute stroke phase." (PMID 36600259, 2023).
Stroke (continued). "It has been reported that electroacupuncture reduces cerebral ischemic injury and neuroinflammatory response in stroke rats through α7nAChR‐mediated inhibition of the NLRP3 inflammasome." (PMID 37088947, 2023). "The suppression of ER stress and/or ROS generation has also been shown to alleviate NLRP3-mediated inflammation in stroke cases by inhibiting Drp1-related mitochondrial function." (PMID 37915409, 2023). "As principal finding we show that infarct progression continues within the subacute stroke stage beyond 24 h after onset and is amenable to anti-inflammatory treatment by NLRP3 inflammasome inhibition." (PMID 36600259, 2023). "We identified candidate blood-based protein biomarkers for post-stroke functional outcome involved in, e.g., NLRP3 inflammasome regulation and signaling pathways, such as TNF, JAK/STAT, MAPK, and NF-κB." (PMID 37794467, 2023). "In recent years, researchers have recognized a new inflammasome signaling pathway, NLRP3 inflammasome containing receptor 3, as a potentially important mediator for detecting cellular injury and mediating post‐stroke inflammation." (PMID 37088947, 2023). "Microglia are indispensable for the inflammatory response after stroke, and NLRP3 is mainly expressed in microglia." (PMID 35419168, 2022). "Gasdermin D-executing pyroptosis mediated by NLRP3 inflammasomes has been recognized as a key pathogenesis during stroke." (PMID 36138981, 2022). "A process that drives neuroinflammation in stroke, for example, a rise in caspase-1 cleavage and release of IL-1β, results from the activation of the NLRP3." (PMID 36138981, 2022). "Recent research has revealed a new inflammatory mechanism that contributes to post‐stroke brain damage, which is mediated by nucleotide‐binding oligomerization domain‐like receptor family, pyrin domain‐containing protein 3 (NLRP3) inflammasomes." (PMID 34866334, 2022). "The ninth- and tenth-ranked articles addressed the involvement of NLRP3 inflammasome in stroke, suggesting the potential clinical value of therapeutic interventions targeting inflammasome assemblies and activities." (PMID 36160384, 2022). "Another study using Adora2a-/- mice showed that inactivation of endothelial ADORA2A protected mice from cerebral ischemia-induced brain injury and improved post-stroke outcomes through anti-inflammatory effects and blockade of NLRP3 inflammasome activity." (PMID 36118760, 2022). "To further address the potential of NLRP3 inflammasome inhibition as adjunct stroke treatment we used immortalized brain derived endothelial cells (bEnd5) as an in vitro model of the BBB." (PMID 35453512, 2022). "Confocal microscopic analysis showed that apocynin increased NLRP3+ cell numbers in the groups treated with apocynin plus 3-MA and rapamycin at 7 and 14 days after stroke compared with rapamycin or 3-MA alone." (PMID 35836200, 2022). "We also observed an increase in p-p65 after MCAO and in NLRP3-KO mice, suggesting that the NF-κB pathway is involved in the inhibition of stroke-induced lung injury." (PMID 35432726, 2022). "The NLRP3 inflammatory signaling pathway is crucial in neurodegenerative diseases, metabolic diseases, autoimmune diseases, atherosclerosis, and stroke." (PMID 35937062, 2022). "Here we found a significant increase in the mRNA levels of Tak1 and the inflammasomes Nlrp3, Nlrc4, and Aim2 after stroke compared to sham surgery." (PMID 34628598, 2022). "Recently, Hettwer and colleagues also reported an involvement of IL‐1β and the NLRP3‐inflammasome pathway in atheroprogression, which is a mechanism of likely relevance also for the inflammatory response after stroke." (PMID 35971650, 2022). "ROS are proposed to serve as upstream signals mediating NLRP3 inflammasome activation and stroke‐induced neuroinflammation." (PMID 35403328, 2022).
Stroke (continued). "Our findings proved that NLRP3 KO not only protects against CIRI but also prevents lung injury induced by stroke." (PMID 35432726, 2022). "The ninth and tenth most highly cited literature, and several other studies, highlighted the importance of NLRP3 inflammasome in the inflammatory response in aseptic tissue involved in acute brain injury after stroke." (PMID 36160384, 2022). "We discover that Li+ inhibits activation of nucleotide-binding oligomerisation domain-like receptor family pyrin domain-containing 3 (NLRP3) inflammasomes in the middle cerebral artery occlusion (MCAO) stroke model in mice." (PMID 35115638, 2022). "In fact, previous studies reported a similar attenuated phenotype for canonical NLRP3 activation (transcription dependent priming) in monocyte-derived macrophages obtained from stroke or AMI patients that was accompanied by decreased IL-1β release." (PMID 35558073, 2022). "It is shown that the neuronal upregulation of NLRP3 is an early event within the first 24 h of cerebral I/R injury which corresponds to the hyperacute and acute phase of human stroke." (PMID 35600078, 2022). "Recently, inhibition of the NLRP3 inflammasome led to preserved blood–brain barrier (BBB) integrity in experimental stroke in vivo." (PMID 35453512, 2022). "Pyroptosis involves the activation of the inflammasome, and the role of the NLRP3 inflammasome in the pathophysiological process of stroke has received increasing attention." (PMID 36311197, 2022). "The NLRP3 inflammasome, which is the best characterized inflammasome to date, contributes significantly to brain injury and neuroinflammation after stroke." (PMID 35836200, 2022). "Our study filled this gap, showing a potential association between NLRP3 and MBE, although possibly confounded by stroke severity." (PMID 34493232, 2021). "The work focused on NLRP3 is the most systematic study, followed by NLRP1, NLRP2, and NLRC4 among the inflammasomes associated with stroke." (PMID 34233704, 2021). "In mice stroke model, the expression of NLRP3 inflammasome was increased in ischemic brain tissue and promoted the damage of BBB, possibly through the pathway of pyroptosis." (PMID 34493232, 2021). "Overall, it would be interesting to learn, what role plays SLURP-1 in the NLRP3 inflammasome induced release of IL1β as this was recently shown to be present in MC and to be attenuated by classical Chrna7 activation in a stroke model." (PMID 33815383, 2021). "The nucleotide-binding oligomerization domain-like receptor family pyrin domain-containing 3 (NLRP3) inflammasome is the most commonly studied inflammasome in stroke." (PMID 34493232, 2021). "Collectively, our in vivo and in vitro models revealed that curcumin suppressed stroke-induced NLRP3 inflammasome activation and pyroptosis in microglial cells." (PMID 34630845, 2021). "Post-stroke inflammasome activation, especially NLRP3, cleaved Caspase-1, cleaved Caspase-11, IL-1β, IL-18, and GSDMD, peaked at 3–5 days and declined at 7 days with the participation of multiple components in mice." (PMID 33967935, 2021). "In particular, stroke was found to evoke microglial pyroptosis-mediated proinflammatory responses via the activation of NLRP3 inflammasome." (PMID 34630845, 2021). "NLRP3 inflammasome-mediated pyroptosis is a proinflammatory programmed cell death pathway, which plays a vital role in functional outcomes after stroke." (PMID 34630845, 2021). "Emerging evidence suggests that NLRP3 inflammasome-mediated microglial pyroptosis plays a crucial role in brain inflammation and functional recovery after stroke." (PMID 34630845, 2021). "Similar to our current study, recent studies have indicated that after stroke, miR-223 can downregulate NLRP3 to negatively regulate caspase-1 and IL-1β to suppress neuroinflammation." (PMID 34408803, 2021). "Western blot results showed that the expressions of both NLRP3 and cleaved caspase-1 were greatly increased after stroke." (PMID 34630845, 2021).